MMP25 (matrix metallopeptidase 25)
Description:
May activate progelatinase A.
Synonyms: MMP-25; MT-MMP 6; MTMMP6; MT6-MMP; MT6MMP; MMP20; MMPL1; MMP20A; MT-MMP6
Tractability: Small molecule: a high-quality ligand is known; it belongs to a druggable protein family. Antibody: its Gene Ontology location is reachable by antibodies, with high confidence; UniProt places it where antibodies can reach, with medium confidence; UniProt predicts a signal peptide or a membrane-spanning region; the Human Protein Atlas places it where antibodies can reach. PROTAC: a small molecule that binds it is known.
Target class: Metallo protease; Metallo protease M10A subfamily; Metallo protease MAM clan; Protease; Enzyme
Gene: Protein-coding gene on chromosome 16 (3,046,062 to 3,060,729, forward strand). Ensembl gene ENSG00000008516.
Subcellular location: Cell membrane; Secreted, extracellular space, extracellular matrix
Subcellular location (Human Protein Atlas): Plasma membrane; Predicted to be secreted
Pathways (Reactome):
Extracellular matrix organization: Activation of Matrix Metalloproteinases
Immune System: Neutrophil degranulation
Gene Ontology:
Molecular function: protein binding; metalloendopeptidase activity; metallopeptidase activity; zinc ion binding
Biological process: collagen catabolic process; extracellular matrix organization; inflammatory response; proteolysis
Cellular component: plasma membrane; extracellular matrix; membrane; specific granule membrane
Genetic constraint (gnomAD): Loss-of-function variants: 68 observed, 57.45 expected, observed/expected ratio (o/e) 1.18, 90% interval 0.97 to 1.45. The synonymous counts are far from expectation, so gnomAD's model fits this gene poorly and the ratio says little. Missense variants: 942 observed, 748.2 expected, observed/expected ratio (o/e) 1.26, 90% interval 1.19 to 1.33. Synonymous variants: 407 observed, 317.51 expected, observed/expected ratio (o/e) 1.28, 90% interval 1.18 to 1.39.
Homologues: Orthologues: chimpanzee MMP25 (98% identical), macaque MMP25 (95% identical), pig MMP25 (84% identical), guinea pig MMP25 (84% identical), dog MMP25 (83% identical), rat Mmp25 (77% identical), mouse Mmp25 (75% identical), tropical clawed frog mmp25 (48% identical), zebrafish mmp17b (36% identical), Caenorhabditis elegans zmp-3 (24% identical), Caenorhabditis elegans zmp-4 (20% identical), Caenorhabditis elegans Y50D7A.13 (13% identical), and 2 more. Paralogues in human: MMP17 (46% identical), MMP14 (36% identical), MMP15 (36% identical), MMP16 (35% identical), MMP24 (34% identical), MMP2 (33% identical), MMP3 (31% identical), MMP10 (30% identical), MMP8 (30% identical), MMP11 (30% identical), MMP13 (29% identical), MMP9 (29% identical), and 11 more.
Diseases named in the same sentence as MMP25 in open-access papers:
MMP25 is named in the same sentence as 46 diseases in open-access papers, as found by Europe PMC text mining. Sharing a sentence is not in itself a finding about the gene and the disease. The quoted sentences say what the papers report.
breast carcinoma (3 papers, 2020 to 2025). "Abnormal methylation of MMP24 and MMP25 was significantly associated with a CpG island hypermethylated breast cancer subtype discovered by genome-wide DNA bisulfite sequencing." (PMID 32397602, 2020). "By MSRE-PCR, we identified abnormal hypermethylation of promoter CpG dinucleotides of five MMP genes, MMP2, MMP23B, MMP24, MMP25, and MMP28, in breast cancer." (PMID 32397602, 2020). "In our collection of 183 breast cancer samples, abnormal hypermethylation was observed for CpGs in MMP2, MMP23B, MMP24, MMP25, and MMP28 promoter regions." (PMID 32397602, 2020).
colorectal cancer (3 papers, 2014 to 2020). A primary or metastatic malignant neoplasm that affects the colon or rectum. "Furthermore, the top 25 of most differentially expressed genes includes two genes that have previously been linked to colorectal cancer: Mmp25 and WT1." (PMID 25243059, 2014). "Functional studies with MMP25-overexpressing colorectal cancer cell lines (HCT−116 and HT−29) have shown that MMP25 upregulation correlates with an increased tumor growth after subcutaneous cell grafting in mice." (PMID 32397602, 2020). "Increased expression of MMP-25, detected by immunohistochemical techniques, has only been reported in colorectal carcinoma samples compared to adjacent tissue." (PMID 24669030, 2014). "In addition, differential expression of genes linked to intestinal bowel disease (i.e. Ccr3, Ccl11 and Tnfr) and colorectal cancer development (i.e. Wt1 and Mmp25) was observed between males and females." (PMID 25243059, 2014).
head and neck cancer (3 papers, 2020 to 2022). A primary or metastatic malignant neoplasm affecting the head and neck. "High expression of MMP25 in head and neck cancer is associated with a worse prognosis; MMP25 is related to apoptosis, the KRS signaling pathway, the PI3K/AKT/mTOR signaling pathway, and the JAK/STAT signaling pathway." (PMID 35060926, 2022). "Expression levels of MMP10, MMP19, MMP24, and MMP25 were associated with prognosis in TCGA cohort of head and neck cancer by Kaplan-Meier analysis." (PMID 32850314, 2020). "Expression levels of MMP10, MMP19, MMP24, and MMP25, which were associated with prognosis in head and neck cancer, were identified using Kaplan–Meier method and log-rank test." (PMID 32850314, 2020). "However, the underlying functions of MMP25 in the head and neck cancer still require further investigation." (PMID 32850314, 2020). "In TCGA cohort, multivariate Cox regression model indicated that MMP25 expression was correlated with clinical stage with prognosis of head and neck cancer patients in terms of overall survival in the TCGA cohort." (PMID 32850314, 2020). "Our results showed that MMP25 high expression was related to head and neck cancer patients' better outcome, and that was regulated by oncogenes and cancer-associated pathways." (PMID 32850314, 2020). "In summary, increased MMP25 expression correlates with better prognosis and increased immune infiltration levels in head and neck cancer, especially activated CD4+ memory T cells." (PMID 32850314, 2020). "Another important result of this study is that MMP25 expression correlated with diverse immune infiltration levels in head and neck cancer." (PMID 32850314, 2020). "The findings shed light on the role of MMP25 in head and neck cancer by providing a potential correlation and a precise mechanism between MMP25 and tumor immune microenvironment." (PMID 32850314, 2020). "In view of the prognostic value of MMP25 in head and neck cancer, we tried to construct the nomogram for predicting 1-, 3-, and 5-year survival." (PMID 32850314, 2020). "In this study, we comprehensively analyzed the mechanism by which MMP25 expression influences the prognosis of head and neck cancer patients." (PMID 32850314, 2020). "Clinicopathological features from TCGA cohort of head and neck cancer showed that high levels of MMP25 expression were correlated with patients' clinical stages in our study." (PMID 32850314, 2020). "In addition, we found that MMP25 had a significant effect on immune infiltration level in head and neck cancer." (PMID 32850314, 2020). "Therefore, our study provides an insight into understanding the role of MMP25 in tumor immune environment and molecular mechanism in head and neck cancer." (PMID 32850314, 2020). "Increased MMP25 expression level could impact the clinical stages of head and neck cancer patients, indicating that MMP25 expression could be used as a potential predictor of clinical stage and prognosis." (PMID 32850314, 2020). "Therefore, we propose that MMP25 probably plays an integral correlative role in immune cell infiltration and can be a potential prognosis biomarker in head and neck cancer." (PMID 32850314, 2020). "Together, these findings suggest that high MMP25 expression levels may be used as a potential prognostic indicator in head and neck cancer." (PMID 32850314, 2020). "However, the molecular mechanism of MMP25 in head and neck cancer pathogenesis remains unclear." (PMID 32850314, 2020). "The TIMER database revealed that MMP25 expression was positively correlated with immune cells infiltration, including B cell, CD8+T cell, CD4+ T cell, and macrophage in head and neck cancers." (PMID 32850314, 2020). "Here, we report that the expression level of MMP25 correlated to the activated CD4+ memory T cells and prognosis in head and neck cancer." (PMID 32850314, 2020).
head and neck cancer (continued). "Univariate Cox proportional hazards regression demonstrated a significant correlation between MMP25 (HR=0.81, p = 0.04) and MMP8 (HR=1.26, p = 0.05) and prognosis of head and neck cancer patients." (PMID 32850314, 2020).
gastric cancer (2 papers, 2015 to 2020). A primary or metastatic malignant neoplasm involving the stomach. "MMP25 is highly expressed in human cancer cells, such as colon cancer cells and gastric cancer cells." (PMID 32850314, 2020). "The aim of the present study was to investigate the expression and clinicopathological features of matrix metalloproteinase 17 (MMP17; also known as MT4-MMP) and MMP25 (also known as MT6-MMP) in gastric cancer." (PMID 25621036, 2015). "The expression of MMP25 in the gastric cancer and atrophic gastritis tissues was markedly higher compared with the normal gastric tissues (P<0.05)." (PMID 25621036, 2015). "In conclusion, the expression of MMP17 and MMP25 was increased in the gastric cancer tissues in the present study." (PMID 25621036, 2015). "The present study compared the expression of MMP17 and MMP25 in gastric carcinoma, atrophic gastritis and normal gastric tissues." (PMID 25621036, 2015). "Immunohistochemistry and reverse transcription-quantitative polymerase chain reaction were used to detect the expression of MMP17 and MMP25 in 42 cases of gastric carcinoma and normal tissues, and 40 cases of atrophic gastritis." (PMID 25621036, 2015). "The expression of MMP25 mRNA in the normal gastric tissues was significantly lower than that in the atrophic gastritis and gastric carcinoma tissues (0.703±0.014, 6.175±0.702 and 7.328±1.235, respectively; t=7.149, t1=6.123; P>0.05)." (PMID 25621036, 2015). "The detection of MMP17 and MMP25 expression may have clinical value in predicting the prognosis of patients with gastric cancer." (PMID 25621036, 2015). "The MMP25 protein and mRNA expression was associated with the depth of tumor invasion, lymph node metastasis and serosal involvement of the gastric cancer patients (P<0.05), but not with age, gender, lesion length or histological grade (P>0.05)." (PMID 25621036, 2015). "However, MMP25-positive staining was significantly higher in the gastric cancer and atrophic gastritis tissues (40/42 and 33/40 cases, respectively), than in the normal gastric tissues (9/42 cases; χ12=44.08; χ2=28.19; P<0.05)." (PMID 25621036, 2015). "MMP25 was expressed in the normal gastric, atrophic gastritis and gastric carcinoma tissues." (PMID 25621036, 2015). "Therefore, this indicates that the expression of MMP17 and MMP25 is increased with the degree of progress of gastric carcinoma." (PMID 25621036, 2015).
melanoma (2 papers, 2022 to 2025). A malignant, usually aggressive tumor composed of atypical, neoplastic melanocytes. "Downstream signaling analyses showed that MCAM drives the activation of ETV4, which in turn modulates the expression and activity of ZEB1 but not MMP25 observed in melanoma." (PMID 40924339, 2025).
viral infection (2 papers, 2023). "Although we focused our follow-up analysis on putative restriction factors, Mmp-25 was the one weanling BCEC enhanced putative susceptibility factor whose knockdown reduced viral infection in primary BCECs, which may warrant further analysis." (PMID 37202395, 2023). "During viral infection or inflammation, MMP25 inactivates alpha-1 proteinase inhibitor (SERPINA1), the major tissue protectant against proteolytic enzymes released by active neutrophils, thus promoting the migration of neutrophils to sites of active inflammation." (PMID 37036007, 2023).
Arthritis (1 paper, 2020). Inflammation of a joint. "MMP25 is involved in the breakdown of the extracellular matrix in normal physiological processes, such as embryonic development, tissue remodeling, and reproduction as well as in disease processes, such as arthritis and metastasis." (PMID 31480194, 2020).
astrocytoma (1 paper, 2020). "Higher levels of the MMP25 mRNA in tumor tissues have been observed in astrocytoma, glioma, rectal cancer, and prostate cancer." (PMID 32397602, 2020).
atrophic gastritis (1 paper, 2015). "In addition, the fact that MMP25 is highly expressed in atrophic gastritis suggests that it may be involved in the early stage of tumor development." (PMID 25621036, 2015).
autoimmune uveitis (1 paper, 2022). An autoimmune form of uveitis (disease). "The increased abundance of MMP25 in our dataset might therefore indicate a similar effect on the BRB in recurrent autoimmune uveitis; however, future migration and motility studies are needed to confirm our hypothesis and shed more light on the role of this molecule in ERU pathogenesis." (PMID 36076947, 2022). "Other MMPs have previously been associated with ERU pathogenesis through changed expression levels in the equine retina and in infiltrated Th1 cells; however, MMP25 has not been investigated in recurrent autoimmune uveitis so far." (PMID 36076947, 2022).
cholesteatoma (1 paper, 2012). A pathologic process characterized by the proliferation of keratinizing squamous epithelium resulting in the accumulation of keratin and cells in the middle ear and/or mastoid. "Some studies have found positive correlations between cholesteatoma aggressiveness and increased levels of MMP25 and MMP910, 23, given the way these enzymes operate biologically." (PMID 22714856, 2012).
cleft palate (1 paper, 2010). Cleft palate is a fissure type embryopathy that affects the soft and hard palate to varying degrees. "MMP-25 may have a functional role in SP formation as genetic scans of the DNA of human cleft palate patients indicate a common mutation at a region upstream of the MMP-25 gene." (PMID 20809987, 2010).
colon cancer (1 paper, 2020). "In addition, MMP25 was highly expressed and promoted tumor growth in colon cancer." (PMID 32850314, 2020).
COVID-19 (1 paper, 2024). A disease caused by infection with severe acute respiratory syndrome coronavirus 2. "However, the human MMP family consists of several genes, and herein we show increased transcript levels of MMP-19, MMP-23B and MMP-25 in relation to disease severity in PBMC from COVID-19 patients, underscoring a role for MMPs beyond that of MMP-9 in COVID-19." (PMID 38957465, 2024).
metastasis (1 paper, 2015). The spread or migration of cancer cells from one part of the body (where they first appeared) to another. "It was identified that the expression of MMP17 and MMP25 was significantly associated with the depth of tumor invasion, lymph node metastasis and serous membrane involvement, but not with patient age and gender, or lesion length, site and histological grade." (PMID 25621036, 2015).
Obesity (1 paper, 2017). Accumulation of substantial excess body fat. "Although no previous human or animal studies have implicated MMP25 in the development of obesity, decreased levels of circulating alpha-1 proteinase inhibitor were associated with increased BMI in Chinese men." (PMID 28814982, 2017).
ovarian carcinoma (1 paper, 2020). A malignant neoplasm originating from the surface ovarian epithelium. "Likewise, recent evidence also revealed that high MMP25 expression levels were correlated with a better overall survival in ovarian cancer." (PMID 32850314, 2020).
prostate tumour (1 paper, 2005). "These proteases could thus participate directly in prostate tumour invasion, and in this regard it is important to note that MMP25 (MT6-MMP) is primarily expressed by the epithelial cancer cells rather than stromal cells." (PMID 15928670, 2005).
pterygium (1 paper, 2021). A wedge-shaped fibrovascular lesion arising from the bulbar conjunctiva and extending to the cornea. "MMP3 was the only MMP/TIMP gene upregulated in pterygium, and only modestly, while MMP2, MMP7, MMP10, and MMP25 were downregulated." (PMID 34769520, 2021).
retinopathy of prematurity (1 paper, 2017). A bilateral retinopathy characterized by neovascularization, scarring, retinal detachment, and eventually blindness. "Levels of THBS1, MMP8, MMP9, MMP25, TIMP2 and TIMP3 increased as severity of BPD and retinopathy of prematurity (ROP) increased, whereas ETS1, LEF1 and SPOCK2 exhibited the opposite trend." (PMID 28103583, 2017).
schistosomiasis (1 paper, 2010). An infectious disease caused by parasitic trematodes of the genus Schistosoma that colonize human blood vessels and release eggs that can cause granulomatous reactions leading to acute (swimmer's itch or acute schistosomiasis syndrome) or chronic disease. "This is the first report of the up-regulation of MMP-23 and MMP-25 during murine schistosomiasis." (PMID 20161726, 2010).
skin cancer (1 paper, 2018). "Because monocyte-derived M2 macrophages produce MMP1 and MMP25 by RANKL stimulation, TAMs in skin cancer of apocrine origin produce MMP1 and MMP25 at the tumor site." (PMID 29410946, 2018).
skin cutaneous melanoma (1 paper, 2023). "In general, the expression of MMP2, MMP13, MMP16, MMP17 and MMP25 were significantly associated with skin cutaneous melanoma (SKCM) patients prognosis, among which MMP2 low expression benefited patients the most." (PMID 36788565, 2023).
tendinopathy (1 paper, 2022). "Previously, there have been a few reports of differential promoter methylation of Mmp25, Foxf1, Leprel2, Igfbp6 and Peg12 in tendinopathy through genome-wide analysis." (PMID 35860629, 2022).